EIF4B (eukaryotic translation initiation factor 4B)
Description:
Required for the binding of mRNA to ribosomes. Functions in close association with EIF4-F and EIF4-A. Binds near the 5'-terminal cap of mRNA in presence of EIF-4F and ATP. Promotes the ATPase activity and the ATP-dependent RNA unwinding activity of both EIF4-A and EIF4-F.
Synonyms: eIF-4B; PRO1843
Tractability: Antibody: the Human Protein Atlas places it where antibodies can reach. PROTAC: UniProt records ubiquitination sites on it; ubiquitination databases record sites on it; its protein half-life has been measured.
Target class: Other nuclear protein
Gene: Protein-coding gene on chromosome 12 (53,006,279 to 53,042,230, forward strand). Ensembl gene ENSG00000063046.
Subcellular location (Human Protein Atlas): Cytosol; Endoplasmic reticulum; Plasma membrane
Pathways (Reactome):
Metabolism of proteins: Activation of the mRNA upon binding of the cap-binding complex and eIFs, and subsequent binding to 43S; GTP hydrolysis and joining of the 60S ribosomal subunit; L13a-mediated translational silencing of Ceruloplasmin expression; Ribosomal scanning and start codon recognition; Translation initiation complex formation
Developmental Biology: M-decay: degradation of maternal mRNAs by maternally stored factors; Z-decay: degradation of maternal mRNAs by zygotically expressed factors
Metabolism of RNA: Deadenylation of mRNA
Signal Transduction: mTORC1-mediated signalling
Gene Ontology:
Molecular function: protein binding; RNA binding; translation initiation factor activity; nucleic acid binding
Biological process: regulation of translational initiation; translational initiation
Cellular component: cytosol; eukaryotic translation initiation factor 4F complex; dendrite; neuronal cell body; postsynapse
Genetic constraint (gnomAD): Loss-of-function variants: 7 observed, 74.75 expected, observed/expected ratio (o/e) 0.0936, 90% interval 0.052 to 0.18. The upper end of that interval is the gene's LOEUF score, 0.18, which puts it in group 1 of 6, group 1 being the genes least tolerant of losing a copy. Missense variants: 499 observed, 766.59 expected, observed/expected ratio (o/e) 0.65, 90% interval 0.6 to 0.7. Synonymous variants: 233 observed, 271.83 expected, observed/expected ratio (o/e) 0.86, 90% interval 0.77 to 0.95.
Homologues: Orthologues: chimpanzee EIF4B (99% identical), macaque EIF4B (98% identical), rabbit EIF4B (93% identical), pig EIF4B (93% identical), tropical clawed frog eif4b (68% identical), zebrafish eif4ba (64% identical), zebrafish eif4bb (57% identical), Drosophila melanogaster eIF4B (26% identical). Paralogues in human: EIF4H (17% identical).
Diseases named in the same sentence as EIF4B in open-access papers:
EIF4B is named in the same sentence as 65 diseases in open-access papers, as found by Europe PMC text mining. Sharing a sentence is not in itself a finding about the gene and the disease. The quoted sentences say what the papers report.
breast carcinoma (7 papers, 2015 to 2023). "One late-type gene (EPN3) was significantly associated with shorter OS, and two late-type genes (RPL3, EIF4B) with longer OS, in more than one cohort, in agreement with findings in breast cancer." (PMID 27926932, 2016). "Abnormal eIF4B levels or phosphorylation are closely related to various tumors, including breast cancer, leukemia, Kaposi’s sarcoma, and lymphoma." (PMID 36897170, 2023). "Recently OTS167 has been shown to inhibit the MELK-dependent phosphorylation of eIF4B in human breast cancer cell lines, which resulted in downregulation of anti-apoptotic factor myeloid cell leukemia 1 (MCL-1) expression." (PMID 33658483, 2021). "Elevated protein expression levels of eIF4A and eIF4B have been observed in breast cancer patients." (PMID 31106142, 2019). "When breast cancer cells with either wild-type (BT474) or activating mutations in both PI3K/Akt/mTORC1 and MAPK pathways (SUM159PT) were analyzed, we observed that the regulation of eIF4B, S6 and PDCD4 mostly relies on the agonist-stimulated pathway." (PMID 27028868, 2016). "Four of the ten late-type genes, the ribosome-related factors EIF4B, RPL5, RPL3, and the tumor angiogenesis modifier EPN3 were significantly associated with MFS in the late period also in a meta-analysis of tamoxifen-treated breast cancer cohorts." (PMID 27926932, 2016). "A large scale tissue microarray study involving about 4,000 patients documented that the expression of eIF4A and eIF4B can predict the clinical outcome in estrogen receptor-negative (ER-) breast cancer and was statistically independent from other known prognostic factors." (PMID 31867270, 2019). "Furthermore, as evident from S7B–S7D Table, several late-type genes showed a significant, but opposite, association with prognosis in one or more cohorts compared to the initial analysis of breast cancer, exemplified by RPL10, EIF4B, GPBP1L1 in NSCLC and RPL3, RPS6 and STEAP1 in ovarian cancer." (PMID 27926932, 2016). "Phosphorylation of eIF4B at S422, S6 at S235/236, 4E-BP1 at S65 as well as the decrease in PDCD4 levels mostly depended on the PI3K/Akt/mTORC1 pathway, under any tested condition, in breast cancer cell lines in which only this pathway was up-regulated (MCF7, T47D, and MDA-MB-468)." (PMID 27028868, 2016). "Three late-type genes, EIF4B, RPL5 and RPL3, were found to be significantly associated with late metastasis in two or more cohorts, all associated with longer MFS in the univariate Cox analysis, in agreement with findings in the node-negative, untreated breast cancer cohorts." (PMID 27926932, 2016). "We show that RSKs regulate the activities of the translation initiation factor eIF4B and the translational repressor PDCD4 in TNBC cells with up-regulated MAPK pathway, but not in breast cancer cells with hyperactivated PI3K/Akt/mTORC1 pathway." (PMID 27028868, 2016).
diffuse large B-cell lymphoma (5 papers, 2016 to 2024). "USP11 stabilizes and enhances Eukayotic translation initiation factor 4B (eIF4B) activity and promotes oncogenic translation in diffuse large B cell lymphoma (DLBCL)." (PMID 36490346, 2022). "Here, in diffuse large B-cell lymphoma, the authors show that fatty acid synthase increases USP11 interaction with and stability of eIF4B via PI3K-S6Kinase signaling, promoting oncogenic protein translation." (PMID 29483509, 2018). "Moreover, in diffuse large B-cell lymphoma (DLBCL), an aggressive form of non-Hodgkin lymphoma, high levels of eIF4B increase the expression of key survival proteins, including BCL-2, DAXX and ERCC5, and are prognostic of poor patient outcome." (PMID 39225047, 2024).
depression (4 papers, 2013 to 2019). "Among them, ubiquitin-fold modifier 1 (UFM1) and eukaryotic translation initiation factor 4B (EIF4B) were highly upregulated in patients who developed IFN-α–induced depression." (PMID 31207337, 2019). "Among the most significant differentially expressed genes at baseline (predictors), we find upregulation of ubiquitin-fold modifier 1 (UFM1) and eukaryotic translation initiation factor 4B (EIF4B) in patients who later develop IFN-α-induced depression." (PMID 27067128, 2016). "Furthermore, other down-stream signaling molecules, such as mTOR, P70S6K, and eIF4B, have been shown to be increased in major depressive disorder." (PMID 29163244, 2017).
gastric cancer (4 papers, 2020 to 2025). A primary or metastatic malignant neoplasm involving the stomach. "Reduced METTL14 increases circORC5 expression and lowers Akt Substrate 1S1 (AKT1S1) and Eukaryotic Translation Initiation Factor 4B (EIF4B) levels by decreasing m6A modification on circORC5, thereby accelerating gastric cancer progression." (PMID 39791162, 2025). "In addition, circORC5 can absorb miR‐30c‐2‐3p, reverse the upregulation of miR‐30c‐2‐3p and downregulation of proline‐rich AKT1 substrate 1 (AKT1S1) and eukaryotic initiation factor 4B (EIF4B) induced by METTL14 and regulate the malignant progression of gastric cancer cells." (PMID 38263865, 2024).
hepatocellular carcinoma (4 papers, 2021 to 2025). A malignant tumor that arises from hepatocytes. "In the same way, the GMAN/p‐EIF4B pathway leads to cell proliferation and invasion in hepatocellular carcinoma (HCC)." (PMID 40705973, 2025). "For instance, LINC00703 suppresses GC cell proliferation and invasion but induces apoptosis and lncRNA GMAN promotes hepatocellular carcinoma progression by interacting with eIF4B." (PMID 34650909, 2021). "LncRNA-GMAN was significantly upregulated in hepatocellular carcinoma (HCC), which can increase the phosphorylation of eukaryotic translation initiation factor 4B (eIF4B) to promote metastasis and inhibit apoptosis in HCC7." (PMID 33993193, 2021). "Additionally, lncRNA-GMAN directly combines with eIF4B, which interferes with the interaction of eIF4B and PP2A B subunit, thereby preventing the dephosphorylation of eIF4B at Ser422 and subsequently increasing the mRNA translation of anti-apoptosis proteins in hepatocellular carcinoma cells." (PMID 34566982, 2021).
leukemia (4 papers, 2016 to 2025). A malignant (clonal) hematologic disorder, involving hematopoietic stem cells and characterized by the presence of primitive or atypical myeloid or lymphoid cells in the bone marrow and the blood. "Moreover, GSPT1 interacted with ELAVL1 and EIF4B, proteins associated with favorable AML outcomes, while KPNA1 negatively interacted with PPP1CA, a marker of poor prognosis, suggesting its role in modulating negative prognostic pathways in leukemia." (PMID 39940906, 2025).
lymphoma (4 papers, 2020 to 2023). A malignant (clonal) proliferation of B- lymphocytes or T- lymphocytes which involves the lymph nodes, bone marrow and/or extranodal sites. "The phosphorylated USP11 mediates eIF4B deubiquitination to increase its stability, and eIF4B promotes key oncogenes biosynthesis, ultimately driving the development of lymphoma." (PMID 36106108, 2022). "USP11 deubiquitinates and stabilizes the translation initiation factor EIF4B to promote EIF4B-dependent oncogenic translation, thus phosphorylating USP11 enhances the stability and abundance of EIF4B, which ultimately facilitates the occurrence of lymphoma." (PMID 35715413, 2022).
viral infection (4 papers, 2019 to 2024). "Strikingly, eIF4B CKO mice were highly susceptible to viral infection with severe pulmonary inflammation." (PMID 34566982, 2021). "Since eIF4B knockout mice were highly susceptible to viral infection, we next evaluated the effect of eIF4B on the pathogenesis of influenza A virus in the lungs." (PMID 34566982, 2021). "In this study, we demonstrated that eIF4B CKO mice were more susceptible to viral infection including influenza virus and pseudorabies virus." (PMID 34566982, 2021). "Furthermore, eIF4B-deficient mice are more susceptible to viral infection; selective deletion of eIF4B in lung epithelium significantly enhances viral replication in the lung." (PMID 34566982, 2021). "Together, these data suggest that disruption of eIF4B may cause excessive production of inflammation-associated factors and chemokines during the viral infection, which might lead to severe pulmonary inflammation in the animals." (PMID 34566982, 2021). "These experiments demonstrate that eIF4B-deficient mice are more susceptible to viral infection." (PMID 34566982, 2021). "Taken together, these observations indicate that knockout of eIF4B impairs the infiltration of NK cells and their function in the lung in response to IAV infection, which may result in high susceptibility of the eIF4B CKO animals to the viral infection." (PMID 34566982, 2021). "In addition, eIF4B is also essential for the animal survival, and antiviral responses of adult mice, as evidenced by markedly increased mortality of eIF4B conditional knockout adult mice, and significantly enhanced susceptibility of eIF4B-deficient animals to viral infection." (PMID 34566982, 2021). "Overall, the results indicate that knockout of eIF4B markedly enhances pulmonary inflammation in response to viral infection." (PMID 34566982, 2021). "To determine the underlying mechanism of enhanced pulmonary inflammation in eIF4B CKO mice during the viral infection, we performed transcriptomic analysis by RNA-seq of lung tissues of eIF4B CKO and WT control mice infected with WSN." (PMID 34566982, 2021). "Moreover, changes in the human phosphoproteome upon viral infection highlighted several RSK target proteins in addition to c-FOS and EIF4B, such as 40S ribosomal protein S6, Tuberin/TSC2, or GSK347." (PMID 35078976, 2022).
Alzheimer disease (3 papers, 2021 to 2023). A progressive, neurodegenerative disease characterized by loss of function and death of nerve cells in several areas of the brain leading to loss of cognitive function such as memory and language. "Some of the candidate genes are also known to play a role in neuronal diseases like Alzheimer’s disease (EIF4B), schizophrenia (CACNG8) or Parkinson’s disease (TNR)." (PMID 36624125, 2023).
colorectal cancer (3 papers, 2017 to 2026). A primary or metastatic malignant neoplasm that affects the colon or rectum. "The S6 kinase activity was shown to decrease in human colorectal cancer cells cultured with cystine-deficient media, suggesting that eIF4B is also involved in the cysteine-dependent translational regulation of D-type cyclins." (PMID 39413876, 2024).
glioma (3 papers, 2019 to 2025). A benign or malignant brain and spinal cord tumor that arises from glial cells (astrocytes, oligodendrocytes, ependymal cells). "EIF4B (Eukaryotic Translation Initiation Factor 4B), with the highest hazard ratio among our markers, suggests that dysregulated protein synthesis may be a key driver of aggressive disease behavior in IDH wild-type gliomas." (PMID 41356219, 2025).
breast tumors (2 papers, 2015 to 2019). "Therefore, immunohistochemical analysis was performed on over 3000 breast tumors to investigate the relationship among expression of eIF4A1, the helicase-modulating proteins eIF4B, eIF4E and PDCD4, and clinical outcome." (PMID 25611378, 2015).
diabetic kidney disease (2 papers, 2022 to 2025). Progressive kidney disorder caused by vascular damage to the glomerular capillaries, in patients with diabetes mellitus. "Also, we established diabetic nephropathy rat models; marker genes (EIF4B, RICTOR, and PRKCB) of the immune cells were confirmed to be up-regulated in diabetic nephropathy." (PMID 35620059, 2022). "The expression of mTOR pathway markers EIF4B, RICTOR, and PRKCB was verified in kidney tissues from the control group and the diabetic nephropathy rat model group." (PMID 35620059, 2022). "Although the expression of EIF4B, RICTOR, and PRKCB was verified in a diabetic nephropathy rat model, a deeper analysis should be conducted for confirming their functions in diabetic nephropathy progression." (PMID 35620059, 2022). "The GSE111154 and GSE142025 datasets were utilized for validating the expression of mTOR pathway markers EIF4B, RICTOR, and PRKCB in the kidneys from controls and diabetic nephropathy patients." (PMID 35620059, 2022). "To verify the expression of EIF4B, RICTOR, and PRKCB proteins, we established a diabetic nephropathy rat model." (PMID 35620059, 2022). "Differentially expressed marker genes of immune cells EIF4B, RICTOR, and PRKCB were significantly enriched in the mTOR pathway, which were confirmed to be up-regulated in diabetic nephropathy." (PMID 35620059, 2022). "Meanwhile, Western blot results confirmed the significant up-regulation of EIF4B, RICTOR, and PRKCB proteins in kidney tissues of diabetic nephropathy rats than that of control rats." (PMID 35620059, 2022). "Our data showed that in comparison to the control group, EIF4B, RICTOR, and PRKCB displayed markedly higher mRNA expression in diabetic nephropathy rats." (PMID 35620059, 2022). "Collectively, marker genes of immune cells EIF4B, RICTOR, and PRKCB in the mTOR pathway might participate in diabetic nephropathy progression." (PMID 35620059, 2022).
epilepsy (2 papers, 2015 to 2017). A brain disorder characterized by episodes of abnormally increased neuronal discharge resulting in transient episodes of sensory or motor neurological dysfunction, or psychic dysfunction. "We investigated how perturbations of synaptic activity modulate the expression, phosphorylation, localization and function of eIF4B in mature hippocampal neurons in culture, and validated our results in vivo taking advantage of the pilocarpine-induced model of epilepsy." (PMID 28874824, 2017).
lung adenocarcinoma (2 papers, 2023 to 2025). A carcinoma that arises from the lung and is characterized by the presence of malignant glandular epithelial cells. "The PIM1 kinase regulates c-MET expression via phosphorylation of eukaryotic translation initiation factor 4B (eIF4B), thus promoting lung adenocarcinoma proliferation." (PMID 37381723, 2023).
melanoma (2 papers, 2002 to 2016). A malignant, usually aggressive tumor composed of atypical, neoplastic melanocytes. "It is thereby reasonable to speculate that MC1R signaling participates in maintaining levels of eIF-4B protein high enough to support robust melanoma cell growth and division." (PMID 27028866, 2016). "This assumption is further promoted by the finding that only eIF-4A1 but none of the other group 4 translation factors (eIF-4E, eIF-4B, eIF-4G, eIF-4A2) was significantly upregulated in melanoma cells as compared to normal melanocytes." (PMID 12085193, 2002).
schizophrenia (2 papers, 2021 to 2023). A major psychotic disorder characterized by abnormalities in the perception or expression of reality. "Studies using the MK-801 (a selective and non-competitive NMDAR antagonist) neurodevelopmental animal model of schizophrenia found an altered p70S6K-S6/eIF4B pathway and protein translation in the frontal cortex of schizophrenic-like rat." (PMID 34630179, 2021).
Sepsis (2 papers, 2014 to 2022). Sepsis is defined as life-threatening organ dysfunction caused by a dysregulated host response to infection. "A comparable sepsis-induced increase in eIF4B phosphorylation was seen in both WT and DKO mice." (PMID 24945486, 2014). "However, in the current study, sepsis increased eIF4B phosphorylation (despite a reduction is S6K1 phosphorylation) in muscle and this increase was comparable between WT and DKO mice." (PMID 24945486, 2014).
Type 2 Diabetes (2 papers, 2025). "The gastrin/CCKBR axis inhibits the expression of SGLT1 and GLUT2 through the PI3K/AKT/eIF4B signaling pathway, thereby preventing type 2 diabetes." (PMID 40733369, 2025).
autism (1 paper, 2015). Persistent deficits in social interaction and communication and interaction as well as a markedly restricted repertoire of activity and interest as well as repetitive patterns of behavior. "In contrast to some monogenic disorders with high rates of autism, our data demonstrate down-regulation of the Akt/mTOR pathway, specifically via p70S6K/eIF4B, in idiopathic autism." (PMID 25627160, 2015). "Conversely, in our study, autistic subjects had significantly decreased p70S6K and eIF4B, while there were no changes in 4E-BP1 or eIF4E in these patients, pointing to specific deficits in mTOR-dependent translation via the p70S6K/S6 pathway in idiopathic autism." (PMID 25627160, 2015).
cervical cancer (1 paper, 2016). A primary or metastatic malignant neoplasm involving the cervix. "Depletion of eIF-4B using silencing RNA in the human cervical cancer line HeLa reduced proliferation by greater than 90% over a five day period and rendered them more sensitive to killing by the topoisomerase inhibitor camptothecin." (PMID 27028866, 2016).
colitis (1 paper, 2021). Inflammation of the colon. "Moreover, we employed the dextran sulfate sodium (DSS)-induced colitis model and sought to examine the role of eIF4B in colonic inflammation." (PMID 34566982, 2021).
colon cancer (1 paper, 2019). "Analysis of TCGA colon cancer (n=461) and skin cancer (n=470) datasets revealed a positive correlation between PHF14 expression and protein translation initiation factors, eIF4E, eIF4B, and RPS6." (PMID 31040906, 2019).